NRG1 (neuregulin 1)
Diseases named in the same sentence as NRG1 in open-access papers (continued):
Sharing a sentence is not in itself a finding about the gene and the disease.
melanoma (continued). "The NRG1/ErbB3/AKT axis has been shown to be involved in adaptive drug resistance in several tumour types, including, breast, lung, prostate, cancer and melanoma." (PMID 31557826, 2019). "Enhanced NRG1/ERBB3 signaling activates the PI3K/AKT pathway and protects melanoma cells against the cytotoxic effect of RAF inhibitors." (PMID 29295999, 2018). "Consistent with previous reports, vemurafenib treatment enhanced ERBB3 expression and improved the sensitivity of melanoma cells to ERBB3 ligand, NRG1, as assessed by the phosphorylation of AKT." (PMID 29295999, 2018). "To investigate the relationship between SOX10, MITF, FOXD3, ERBB3 and NRG1 in patient samples, we utilized The Cancer Genome Atlas (TCGA, SKCM), which contains a set of 474 melanoma patient samples." (PMID 27391157, 2016). "Our work demonstrates that fibronectin secreted in response to vemurafenib treatment can augment RTK signaling in melanoma cells, allowing them to take full advantage of the growth factors (HGF and NRG-1) secreted from fibroblasts." (PMID 26622938, 2015). "Similarly, a direct link between CAF-derived NRG1 and the promotion of therapy resistance via ErbB3 receptor signaling was observed in BRAF-mutant melanoma and prostate cancer." (PMID 40524253, 2025). "We also noted that treatment with recombinant NRG1 did not promote HER3 signaling in the melanoma cell lines utilized in our experiments." (PMID 33327495, 2020). "All these approaches confirmed the validity of the autocrine loop model, the most compelling proof of this was the demonstration that antibodies against NRG1 synergize with a BRAFi in the inhibition of melanoma cell growth in the absence of exogenously added NRG1." (PMID 31557826, 2019). "Furthermore, to confirm that phosphorylation of ErbB3 receptor is a consequence of increased NRG-1 production by melanoma cells we decided first to treat WM266 melanoma cells with vemurafenib (0.5 μM) or not for 24 h." (PMID 31557826, 2019). "Our work has shown a subset of melanoma cells to secrete transforming growth factor-beta (TGF-β) in response to vemurafenib treatment, and this TGF-β, in turn, activates dermal fibroblasts that then express alpha-smooth muscle actin, produce fibronectin and secrete neuregulin (NRG-1)." (PMID 26622938, 2015). "Additionally, our study identified NRG1 fusions in melanoma, which have never been found before." (PMID 36612279, 2022). "Interestingly our data confirm in all BRAF mutated melanoma cell lines analysed that FOXD3 mRNA is upregulated, however it never precedes temporally upregulation of NRG1, which, to our opinion, remains therefore the principal driver of adaptive resistance to BRAF and MEK inhibitors." (PMID 31557826, 2019). "Neither the treatment with recombinant BTC nor that with NRG1 and NRG2 altered the activation of HER3 and STAT3 in A375 melanoma cells." (PMID 33327495, 2020).
ovarian carcinoma (22 papers, 2011 to 2025). A malignant neoplasm originating from the surface ovarian epithelium. "Recent reports have found NRG1 to be a key gene associated with chemotherapy response in ovarian carcinoma and its downregulation correlated with tumor sensitivity to treatment." (PMID 34758842, 2021). "Secondly, seribantumab—a monoclonal antibody that blocks HER3 activation by NRG1—led to the inhibition of NRG1 fusion-dependent tumor growth in patient-derived breast, lung, and ovarian cancer models." (PMID 41374970, 2025). "In ovarian cancers, increase of the neuregulin 1 (NRG1)/Erb-B2 receptor tyrosine kinase 3 (ERBB3) pathway has been found to contribute to SINE resistance." (PMID 39050883, 2024). "Fusions of NRG1 and a few different partner genes have been described in other tumors as well, namely in ovarian cancer: SETD4, TSHZ2, ZMYM2, RAB3IL1, and CLU, and in pancreatic ductal adenocarcinoma: VTCN1, CDH1, CDH6, SARAF, APP, and CDK1." (PMID 39123493, 2024). "This drug was first proven in pre-clinical models of lung, breast, pancreas, and ovarian cancers with neuregulin-1 (NRG1) fusions in both in vitro and in vivo settings." (PMID 37370772, 2023). "For example, seribantumab (MM-121), a neutralizing mAb against ErbB3, significantly reduced tumor growth in xenograft models of lung and ovarian cancer derived from patients with carcinogenic neuregulin 1 (NRG1) fusion." (PMID 36293051, 2022). "Other studies revealed that induced expression of BRD4 isoforms in ovarian epithelial cells correlates with increased expression of NRG1, which has been shown to participate in ovarian cancer cells proliferation and metastasis." (PMID 34758842, 2021). "BRD4 directly binds to two independent NRG1 promoter and enhancer sites, and NRG1 has been identified as a direct effector of BRD4 in ovarian carcinoma." (PMID 34758842, 2021). "As it relates to HGSOC patients, NRG1 has been shown to drive proliferation of ovarian cancer cells in the context of activated ErbB3/NRG1 autocrine signaling." (PMID 30036377, 2018). "NRG1 has been shown to contribute to proliferation, survival and metastasis of ovarian cancer cells." (PMID 30036377, 2018). "Elevated levels of Human Epidermal Growth Factor Receptor 3 (ErbB3/HER3) in ovarian cancer cells and Neuregulin 1 (NRG1) in the omentum allowed for tumor cell localization and growth in the omentum." (PMID 29389895, 2018). "NRG-1 was able to stimulate HER2 phosphorylation in the A2780 ovarian cancer cells, in agreement with the expression of HER3 and HER4 mRNA in these cells." (PMID 27543060, 2016). "More recently, an activated ERBB3/NRG1 autocrine loop has been demonstrated to support tumor cell proliferation in a subset of primary ovarian cancers and ovarian cancer cell lines." (PMID 21962244, 2011). "On the other hand, an ErbB4 antibody that blocks ErbB4 and NRG1 interaction appeared to have a stimulatory effect in some of the ovarian cancer cell lines tested, suggesting a possible role for ErbB4 in growth inhibition in these cells." (PMID 21364581, 2011). "More recently, signalling through the ErbB3 pathway has been reported to correlate with expression of its natural ligand, neuregulin-1 (NRG1) in both ovarian cancer cell lines and in primary human ovarian cancer cells." (PMID 21364581, 2011). "Moreover, we queried the whole transcriptome sequencing results of neoplasms analyzed by a commercial laboratory (Caris Life Sciences) to determine the overall incidence of NRG1 fusions in carcinomas of the ovary, fallopian tube, and peritoneum (0.18%)." (PMID 39575425, 2024). "Interestingly, this miRNA was also found as a regulatory element for genes such as PTEN, SMAD4, ESR1, NRG1, etc., in the miRWalk database for ovarian carcinoma." (PMID 36899893, 2023). "• Establishment of ovarian cancer organoid model.• Importance of heregulin-β1 (neuregulin-1)." (PMID 33959613, 2021).
ovarian carcinoma (continued). "Additionally, it was found in ovarian cancer that NRG1 activated HER3 and promoted proliferation and cancer progression." (PMID 33327495, 2020). "In serous ovarian cancer, the ERBB4 CYT-1 variant we expressed in Ba/F3 cells was identified as independent prognostic factor for survival, and may cooperate with NRG1 autocrine signaling to support ERBB3-mediated ovarian cancer cell proliferation in vivo." (PMID 26745281, 2016). "Expression of NRG1 has been observed in 30–83% of ovarian carcinomas." (PMID 21364581, 2011). "Hence, transcriptional modulation of the NRG1 pathway might be one of the mechanisms through which BRD4 plays a role in ovarian cancer patients’ response to chemotherapy, however, further studies are required to validate such mechanism." (PMID 34758842, 2021). "Furthermore, in a subset of ovarian cancer cells that display an NRG1-expressing/phosphorylated-ErbB3 phenotype, depletion of ErbB3 by RNA interference (RNAi) could result in anti-proliferative effects in vitro." (PMID 21364581, 2011). "Expression of NRG1 and ERBB3, as well as NRG1 secretion, were increased in SINE-resistant ovarian cancer cells." (PMID 39050883, 2024). "The prevalence of NRG1 rearrangements in other types of cancers is similar to NSCLC and amounts to 0.5% in cholangiocarcinoma, pancreatic carcinoma, and renal cell carcinoma, 0.4% in ovarian cancer, and 0.2% in breast cancer and sarcoma." (PMID 39123493, 2024).
prostate carcinoma (21 papers, 2019 to 2026). A carcinoma that arises from epithelial cells of the prostate gland. "Lower NRG1 expression was associated with significantly poor PFS in patients with prostate cancer (p = 0.014)." (PMID 34068503, 2021). "Although we observed some associations between NRG1 and prostate cancer supported by multiple functional data, the exact molecular mechanisms remain to be elucidated." (PMID 34068503, 2021). "High neuroligin levels also correlate with high levels of prostate-specific antigen (PSA) and Gleason grading, both associated with more aggressive disease, suggesting that NRG1 could be a marker for predicting progression of prostate cancer." (PMID 41516419, 2026). "Although this evidence supports our findings that NRG1 may have a protective effect in prostate cancer and its loss may worsen patient prognosis, the exact mechanisms need to be further investigated." (PMID 34068503, 2021). "Moreover, downregulation of NRG1 is associated with prostate cancer progression and decreased PFS in patients." (PMID 34068503, 2021). "Moreover, another study showed that fibroblast-derived NRG1 caused anti-androgen resistance in prostate cancer cells." (PMID 33327495, 2020). "To further investigate the factors secreted by CAFs that enhance PTX resistance in BC cells, we reviewed the literature and found that CAFs promote anti-androgen resistance in prostate cancer and trastuzumab resistance in BC through the secretion of NRG1." (PMID 41213930, 2025). "Based on existing literature, CAF-derived NRG1 has been shown to enhance anti-androgen resistance in prostate cancer and trastuzumab resistance in BC." (PMID 41213930, 2025). "Due to that androgen deprivation with bicalutamide or enzalutamide -each a commonly prescribed anti-androgen for patients with prostate cancer- drives additional NRG1 production." (PMID 40740239, 2025). "This study is the first to evaluate the predictive value of NRG1 in prostate cancer patients before ADT, for predicting CRPC progression during ADT within one year." (PMID 40740239, 2025). "While ASPN expression is restricted to the stroma of prostate cancer metastases, NRG1 expression has been reported in cancer cells." (PMID 40857406, 2025). "Previous data showed that serum PSA levels were associated with CRPC, therefore the correlation between serum PSA levels and NRG1 levels in prostate cancer before ADT was explored." (PMID 40740239, 2025). "In prostate cancer, the tumor microenvironment-derived NRG1 activates the HER3 gene to promote antiandrogen resistance." (PMID 37205121, 2023). "We found that the mRNA expression of NRG1 was lower in prostate cancer than in normal tissues, and the low expression levels were associated with shorter patient PFS." (PMID 34068503, 2021). "Regarding NRG1, it has been recently demonstrated that it is released by the tumor microenvironment and promotes antiandrogen resistance in prostate cancer." (PMID 34440012, 2021). "Together, these findings indicate that NRG1 has potential anti-tumorigenic effects in prostate cancer." (PMID 34068503, 2021). "Meta-analysis of 16 gene expression datasets of 1,081 prostate cancer samples and 294 adjacent normal samples indicate lower NRG1 expression in the former compared with the latter (p < 0.001)." (PMID 34068503, 2021). "Further analysis showed that low expression of NRG1 is closely related to prostate cancer, as indicated by a high Gleason score, an advanced stage, and a shorter PFS rate." (PMID 34068503, 2021). "Further studies are required to confirm the significance of NRG1 as a biomarker and therapeutic target for prostate cancer." (PMID 34068503, 2021). "Therefore, the correlation of the Gleason score to NRG1 in 237 prostate cancer patients before ADT was analyzed." (PMID 40740239, 2025). "In prostate cancer, CAFs-derived NRG1 promotes antiandrogen resistance through HER3 activation." (PMID 40959099, 2025).
prostate carcinoma (continued). "The clinical relevance of NRG1 in prostate cancer was further assessed using a TCGA PRAD dataset." (PMID 34068503, 2021). "Since downregulation of NRG1 in prostate cancer was associated with a higher Gleason score, more advanced-stage tumours, and worsening patient PFS, it can be stated that NRG1 plays a tumor suppressive role in prostate cancer." (PMID 34068503, 2021). "Therefore, the mechanism by which NRG1 rs144160282 affects the efficacy of ADT in patients with prostate cancer needs to be further investigated." (PMID 34068503, 2021). "Our study indicates that NRG1 levels can augment the predictive value of PSA and Gleason score in forecasting CRPC progression in prostate cancer patients." (PMID 40740239, 2025). "Studies have shown that paracrine NRG1 secreted by CAFs can bind to human epidermal growth factor receptors 2/3 (HER2/3) on tumor cells, enhancing anti-androgen resistance in prostate cancer." (PMID 41213930, 2025). "The PSA levels are also associated with the prognosis and progression of CRPC in PC patients, therefore, our results further suggest the correlation between NRG1 levels and the progression of CRPC in prostate cancer patients." (PMID 40740239, 2025). "In prostate cancer, CAF-derived NRG1 can promote resistance to anti-androgen therapy by stimulating ERBB2/ERBB3 heterodimers in cancer cells." (PMID 36357571, 2023). "In prostate cancers, CAF-derived neuregulin 1 NRG1 promotes resistance in tumor cells by activating HER3 involving the NRG1/HER3 axis, proving a paracrine mechanism of antiandrogen resistance in a paracrine manner, as presented above." (PMID 35326670, 2022). "Therefore, our study aims to analyze the value of serum NRG1 levels in prostate cancer patients before ADT, as well as NRG1 levels in biopsy tissues and NRG1 gene expression, for predicting CRPC progression within one year of ADT." (PMID 40740239, 2025). "CAF-derived NRG1 promoted resistance in tumor cells through the activation of HER3 involving the NRG1/HER3 axis, proving a paracrine mechanism of anti-androgen resistance in prostate cancer." (PMID 35326670, 2022). "The expression level of NRG1 mRNA decreased in prostate cancer as compared to adjacent noncancerous tissues (p < 0.001)." (PMID 34068503, 2021). "In this study, we found that NRG1 rs144160282 could independently predict CSS, OS, and PFS following ADT among patients with prostate cancer." (PMID 34068503, 2021).
glioma (19 papers, 2015 to 2026). A benign or malignant brain and spinal cord tumor that arises from glial cells (astrocytes, oligodendrocytes, ependymal cells). "In conclusion, our model, based on AS genes, effectively predicts glioma prognosis, identifying NRG1 as a significant marker." (PMID 41578499, 2026). "RNAi-mediated PSEN2 inhibition was found to suppress glioma cell growth and invasion by regulating Nrg1/ErbB signaling." (PMID 39213172, 2024). "Inhibition of ERBB receptors can lead to suppression of cancer cell migration and inhibition of NRG1/ERBB2 signaling reduces migration of human glioma cells." (PMID 36239094, 2022). "On the contrary, NRG1 expression is positively correlated with immune scores, stromal scores and ESTIMATE scores (P < 0.01 for all scores) in GBM, suggesting that NRG1 plays opposite roles in different grades of gliomas." (PMID 34054873, 2021). "Nrg1 was directly regulated by miR-125a-3p, which in turn led to the inhibition of glioma cell proliferation and invasion." (PMID 32046740, 2020). "Previous studies have demonstrated that NRG1 plays an important role in aspects of glioma development and progression, including cell survival, migration, proliferation, and metastasis." (PMID 31844032, 2019). "We previously reported that cell adhesion molecule L1 (L1CAM) is involved in regulating tumor progression and invasion under the modulation of Neuregulin-1 (Nrg1), suggesting the roles of L1 family members in glioma development." (PMID 29089868, 2017). "Nrg1 has been shown to promote the invasive behavior of breast cancer cells and the motility and migration of human glioma cells." (PMID 25560389, 2015). "It has shown that miR-125a-3p is down-regulated in malignant gliomas and that miR-125a-3p overexpression potently inhibits glioma growth and invasion by targeting a tumor suppressor-Nrg1." (PMID 25560389, 2015). "We also provide evidence to show that miR-125a-3p inhibits glioma cell proliferation and invasion both in vitro and in vivo by regulating Nrg1." (PMID 25560389, 2015). "Mendelian randomization analysis highlighted the significance of NRG1 in glioma development." (PMID 41578499, 2026). "NRG1 expression correlates with a shorter survival in patients with glioma, which could be related to its role in cell migration and proliferation." (PMID 39210279, 2024). "It has been reported that among these tumor suppressors, Nrg1 is dysregulated in glioma and could promote human glioma cell motility and migration." (PMID 25560389, 2015). "Therefore, we concluded that Nrg1 may play an important role in mediating miR-125a-3p functions in glioma development." (PMID 25560389, 2015). "In the GEPIA database, we found that IKBIP was upregulated in glioma relative to normal tissue, while CCBE1, NRG1, and RGS4 were downregulated in glioma." (PMID 34897031, 2021). "In addition, the previous researches had also shown cytokine neuregulin 1 (Nrg1) could upregulate the L1CAM expression to enhancing the migration of glioma cells, and TGF-β1 could mediate L1CAM expression, then led to the downregulation of caspase-8 and apoptosis resistance." (PMID 32509846, 2020). "We treated glioma cells with the following recombinant ErbB family ligands: EGF, NRG1, and HB-EGF protein." (PMID 29864158, 2018). "Furthermore, the study also showed that the expression of Nrg1 in glioma specimens was negatively correlated with the expression of miR-125a-3p, and that there was a positive correlation between the expression of Nrg1 and the survival time of the same cohorts of patients (p<0.01) (right)." (PMID 25560389, 2015). "Unexpectedly, no NRG1 fusion events were identified in sarcoma or glioma, although the sample numbers of both tumor types were greater than 0.2%." (PMID 40730881, 2025).
glioma (continued). "The results showed that NRG1 (p=0.0045), NRG3 (p=0.0073) and NRG4 (p=0.026) were significantly related to survival in recurrent gliomas (all WHO grade), and NRG2 (p=0.031) and NRG3 (p<0.0001) were significantly related to survival in primary gliomas (all WHO grades)." (PMID 34054873, 2021). "Copy number analysis of all glioma cell lines in CCLE revealed that there is a potential mutually exclusive relationship between loss in ERBB4 and loss in NRG1 as ERBB4 and NRG1 copy number loss never occur simultaneously." (PMID 29342193, 2018). "We did not capture NRG1 fusion events in sarcoma and glioma." (PMID 40730881, 2025). "Furthermore, NRG3 and NRG1 may serve as potential independent biomarkers in LGG and GBM in clinical applications, respectively, including glioma diagnosis and drug development." (PMID 34054873, 2021).